IGF2BP3 (insulin like growth factor 2 mRNA binding protein 3)
Diseases named in the same sentence as IGF2BP3 in open-access papers (continued):
Sharing a sentence is not in itself a finding about the gene and the disease.
Obesity (6 papers, 2022 to 2025). Accumulation of substantial excess body fat. "Next, we verified the downregulation of IGF2BP3 in the colon tissues of patients with obesity-related SAP." (PMID 39856555, 2025). "Overall, an increase in TNF-α impaired the stability of IGF2BP3-dependent CLDN11 mRNA in obesity-related SAP, aggravating intestinal permeability and pancreatic inflammation." (PMID 39856555, 2025). "Overall, the TNF-α/IGF2BP3/CLDN11 axis was involved in the mechanism of obesity-mediated SAP exacerbation and suggests potential therapeutic targets." (PMID 39856555, 2025). "Mechanistically, an increase in TNF-α impaired the stability of IGF2BP3-dependent CLDN11 mRNA in obesity-related SAP." (PMID 39856555, 2025). "In this study, we found the abnormal expression of SQLE was regulated by the methyltransferase Wilms tumor 1-associated protein (WTAP), demethylases fat mass and obesity-associated (FTO), and the insulin-like growth factor 2 mRNA binding protein 3 (IGF2BP3)." (PMID 39617776, 2024). "Fourth, the size of the data set sample and study population is relatively small and the direct evidence of serum IGF2BP3 contribution to overall obesity and central obesity individuals is relatively insufficient." (PMID 36891946, 2023). "In this study, we aimed to clarify the role of CLDN11 in the intestinal epithelial cells of obesity-related SAP and investigate the regulatory mechanism of IGF2BP3 on CLDN11 under inflammatory conditions." (PMID 39856555, 2025). "Under the effect of TNF-α in obesity-related SAP, the transcription and translation of IGF2BP3 in intestinal epithelial cells were inhibited, thereby affecting the expression of CLDN11." (PMID 39856555, 2025). "Our analysis suggested significant enrichment (corrected P‐value < 0.01) in various catalogs, including obesity‐related traits (e.g., GMDS, PRKG1, and BMP2), Height (e.g., IGF2BP3, BMP2, and BMP3), and Body mass index (e.g., BMP2)." (PMID 40167159, 2025). "Both IGF2BP3 and CLDN11 were downregulated in the intestinal epithelium of patients with obesity-related SAP." (PMID 39856555, 2025). "Anti-TNFα therapy reduced intestinal permeability, alleviated pancreatitis, and improved the expression of IGF2BP3 and CLDN11 in intestinal epithelial cells in experimental obesity-related SAP." (PMID 39856555, 2025). "In six m6A-RMRs upregulated in the obesity group, two regulators IGF2BP3 (RNA methyltransferase) and G3BP1 (m6A repelled RNA binding protein) were shared by obesity IS and obesity IR." (PMID 35211628, 2022).
sarcoma (6 papers, 2015 to 2024). A usually aggressive malignant neoplasm of the soft tissue or bone. "For this we selected three RBPs which are among the top 20% most elevated in the sarcoma interactomes: IGF2BP3, MEX3A and AKAP1." (PMID 38561347, 2024). "Among sarcomas, leiomyosarcoma and chondrosarcoma express IGF2BP3, whereas their benign counterparts, leiomyoma and chondroma, are negative." (PMID 32293476, 2020). "IGF2BP3 is expressed in a variety of carcinomas and sarcomas." (PMID 32293476, 2020).
lung squamous cell carcinoma (5 papers, 2017 to 2024). "Immunohistochemistry showed that IGF2BP3 was expressed in 27–55% of cases of primary pulmonary adenocarcinoma and in 75–90% of cases of squamous cell carcinoma of the lung." (PMID 29212181, 2017).
osteoarthritis (5 papers, 2022 to 2025). A noninflammatory degenerative joint disease occurring chiefly in older persons, characterized by degeneration of the articular cartilage, hypertrophy of bone at the margins and changes in the synovial membrane. "Arthrosis appearance and the micro-CT analysis also showed that the paws of the IGF2BP3-KO arthritis mice exhibited less swelling and less bone destruction than the paws of the WT arthritis mice." (PMID 40355406, 2025). "Notably, the identified here interactions between hsa-let7b/i, hsa-miR-221/222-3p, hsa-miR-302c, hsa-miR-181a, hsa-miR-331 with target genes HMGA2, IGF2BP3, STARD4, and APOL6 could prove to be the necessary tools that will convey iMSCs into the ideal mean for cell therapy in osteoarthritis." (PMID 37443790, 2023).
osteosarcoma (5 papers, 2021 to 2026). A usually aggressive malignant bone-forming mesenchymal neoplasm, predominantly affecting adolescents and young adults. "This positive feedback loop presents a particularly interesting drug target because of the multiplicity of RBPs involved in translation control, including IGF2BP3, regulated by Myc in these “translation-hungry” osteosarcoma cells." (PMID 38561347, 2024). "Taken together, these data indicate that the positive feedback loop involving the RBP IGF2BP3 and the transcription factor Myc represent a vulnerable oncogenic signature of osteosarcoma." (PMID 38561347, 2024). "In the future, we will further explore whether IGF2BP3 functions as a downstream effector that mediates the m6A-dependent stabilization of SNHG1 in osteosarcoma." (PMID 40510136, 2025). "High level of IGF2BP3/IMP3 expression has been associated with metastatic OS in earlier studies, including in a microarray analysis comparing differentially expressed genes between metastatic and non‐metastatic osteosarcoma cells." (PMID 38561347, 2024). "Notably, aberrant expression of insulin-like growth factor 2 mRNA binding protein 3 (IGF2BP3) is correlated with osteosarcoma’s metastasis to the lungs." (PMID 34069554, 2021). "Several m6A genes, including METTL3, RBM15, IGF2BP3, and RNA-binding motif protein X (RBMX), were significantly upregulated in OS cell lines and OS tissues compared to osteoblast and non-osteosarcoma tissues." (PMID 40510136, 2025). "This study aimed to comparatively characterize three canine osteosarcoma cell lines (OSCA8, OSCA29, and D17) in reference to canine hTERT fibroblasts, and with a focus on functional properties and selected molecular features, namely including miR-27b-3p and IGF2BP3 expression." (PMID 42193889, 2026).
ovarian clear cell cancer (5 papers, 2012 to 2022). An invasive malignant neoplasm that arises from the ovary and is characterized by a predominance of clear and hobnail malignant epithelial cells. "Liu and his team found that high expression of IGF2BP3 in clear cell ovarian carcinoma was associated with poor prognosis, and IGF2BP3 was also confirmed to promote the occurrence of clear cell ovarian carcinoma in vivo and in vitro." (PMID 35980273, 2022). "The volume of tumors decreased and cancer metastasis indicator proteins were downregulated after treated with IGF2BP3 siRNA in ovarian clear cell carcinoma." (PMID 36545327, 2022). "Correlations of the IGF2BP3 protein expression levels with the clinicopathological features of ovarian clear cell carcinoma." (PMID 32083017, 2019). "IGF2BP3 is considered to be the first biomarker of prognostic significance in ovarian clear cell carcinoma." (PMID 23226446, 2012). "In fact, IGF2BP3 might differentiate normal tissues from cancerous tissues and serve as a prognostic marker for colorectal, hepatocellular, and ovarian clear-cell carcinomas." (PMID 33246429, 2020).
renal papillary cell carcinoma (5 papers, 2019 to 2022). "We identified 5 mRNAs that are associated with the survival of patients with papillary renal cell carcinoma,namely CCNB2, IGF2BP3, KIF18A, PTTG1, and BUB1 in the training set." (PMID 30822312, 2019). "In general, the 5-mRNA (CCNB2, IGF2BP3, KIF18A, PTTG1, and BUB1) were identified and validated, which can predict papillary renal cell carcinoma patient survival." (PMID 30822312, 2019).
bladder tumor (4 papers, 2022 to 2024). "There are studies that have reported the negative correlation between insulin-like growth factor 2 messenger RNA-binding protein 3 (IGF2BP3) and the prognosis of various tumors, such as bladder tumor prognosis." (PMID 37505298, 2024). "IGF2BP3 mRNA expression was significantly upregulated in bladder tumor tissues compared to normal tissues from the TCGA-BLCA data sets." (PMID 36732736, 2023). "IGF2BP3 can inhibit the apoptosis of bladder tumor cells by activating the JAK/STAT pathway." (PMID 37505298, 2024).
colon adenocarcinoma (4 papers, 2021 to 2023). "To test this prediction, we treated colon adenocarcinoma cell line RKO cells with a lower IGF2BP3 level with 3-deazaadenosine (DAA), an inhibitor of internal N6-methyladenosine." (PMID 37658049, 2023).
cutaneous melanoma (4 papers, 2021 to 2022). A primary melanoma arising from atypical melanocytes in the skin. "In this study we retrospectively analyzed the gene and protein expression of IGF2BP3 in primary cutaneous melanomas, by RT-qPCR and IHC, respectively, and compared them with clinical and histopathological variables and with prognostic parameters." (PMID 35565448, 2022). "The joint verification of TCGA and GTEx also showed that IGF2BP3 was significantly up-regulated in cutaneous melanoma." (PMID 34737950, 2021). "Through the screening of two sets of GEO data sets, we found that IGF2BP3 was significantly up-regulated in cutaneous melanoma." (PMID 34737950, 2021). "In previous studies, IGF2BP3 was highly expressed in most tumor tissues except cutaneous melanoma." (PMID 35677634, 2022). "However, increased levels of IGF2BP3 have been identified in many cancers including adenocarcinomas of the pancreas, kidney, lung, breast, esophagus, cervix, endometrium, and cutaneous melanomas." (PMID 35565448, 2022). "In addition, WTAP, YTHDC1 and YTHDC2 are widely positively correlated with anti-tumor immune-related genes, while IGF2BP3 is widely negatively correlated with these genes, which may be involved in the immune escape of skin melanoma cells." (PMID 34737950, 2021). "Therefore, it is observed that the up-regulation of IGF2BP3 expression is consistent with the up-regulation of mTORC1 signal including PI3K-AKT-MTOR signal pathway, which plays a synergistic role in the growth and metabolism of skin melanoma and tumor immunity." (PMID 34737950, 2021).
esophageal squamous cell carcinoma (4 papers, 2021 to 2023). Esophageal squamous cell carcinoma (ESCC) is a type of esophageal carcinoma (EC) that can affect any part of the esophagus, but is usually located in the upper or middle third. "LINC01305 has been shown to regulate the target gene HTR3A mRNA through interaction with IGF2BP2 and IGF2BP3, thereby participating in the metastasis and proliferation of esophageal squamous cell carcinoma." (PMID 36204323, 2022). "METTL3, WTAP, IGF2BP3, YTHDF1, HNRNPA2B1 and HNRNPC were markedly increased in esophageal squamous cell carcinoma (ESCC) and positively related to the expression of PD-1, whose copy number dynamically affects the enrichment of tumor-infiltrating immune cells." (PMID 36225914, 2022).
intrahepatic cholangiocarcinoma (4 papers, 2022 to 2025). A carcinoma that arises from the intrahepatic bile duct epithelium in any site of the intrahepatic biliary tree. "Moreover, IGF2BP3 protein levels were shown to be specifically expressed in intrahepatic cholangiocarcinoma compared to the surrounding normal tissue." (PMID 34894048, 2022). "Nevertheless, IGF2BP3 was analyzed by RT-qPCR in intrahepatic cholangiocarcinoma (ICC) to validate the results previously observed using IHC." (PMID 35565448, 2022). "PAX8‐AS1 drives chemoresistance in intrahepatic cholangiocarcinoma by activating NRF2‐mediated GPX4 transcription and stabilizing GPX4 mRNA via IGF2BP3." (PMID 40391780, 2025).
malignant glioma (4 papers, 2023 to 2025). A grade III or grade IV glioma arising from the central nervous system. "One study found the presence of IGF2BP3-induced neutrophil extracellular trap (NET) formation in malignant glioma, and blocking this process by a BET inhibitor can enhance VSVΔ51 replication." (PMID 41296382, 2025). "For example, IGF2BP3 tends to exert oncogenic effects in most malignant gliomas in which IGF2BP3 is overexpressed and plays a role in promoting proliferation, invasion, migration, angiogenesis, and chemoresistance." (PMID 38053093, 2023). "Oncolytic herpes simplex virus (oHSV) stimulates IGF2BP3-induced NET formation in malignant glioma." (PMID 38167409, 2024). "This treatment led to increased overexpression of insulin-like growth factor 2 mRNA-binding protein 3 (IGF2BP3), a carcinoembryonic protein that is overexpressed in many tumors such as malignant gliomas." (PMID 39062119, 2024).
multiple myeloma (4 papers, 2018 to 2022). "IGF2BP3 controls CD44, a glycoprotein that has been associated with current therapy resistance in multiple myeloma." (PMID 36076951, 2022). "In multiple myeloma, IGF2BP3 expression is inhibited by miR-9-5p, which is upregulated after AR-42 treatment, a histone deacetylase inhibitor." (PMID 36076951, 2022). "In multiple myeloma (MM), insulin-like growth factor 2 mRNA binding protein 3 (IGF2BP3) stabilizes the expression of a cell surface glycoprotein CD44 that is involved in drug resistance of MM cells." (PMID 29755694, 2018).
squamous cell carcinoma (4 papers, 2017 to 2023). A carcinoma arising from squamous epithelial cells. "At the tissue level, previous study has shown IGF2BP3 is higher expressed in squamous cell carcinoma and adenocarcinoma." (PMID 32984260, 2020). "Histologically, IGF2BP3 is more likely to be expressed in squamous cell carcinoma and adenocarcinoma." (PMID 29212181, 2017). "By tissue microarray, we found that consistent with a previous study, IGF2BP3 is more likely to be expressed in squamous cell carcinoma and adenocarcinoma." (PMID 29212181, 2017). "Moreover, both mRNA and protein levels of IGF2BP3 were remarkably up-regulated in cutaneous squamous cell carcinoma and IGF2BP3 was also identified as a novel therapeutic target for squamous cell carcinoma." (PMID 36761737, 2023). "Besides, elevated IGF2BP3 mRNA levels were also observed in adenocarcinoma, squamous cell carcinoma and large cell carcinoma compared to normal lung tissues in the Hou and Landi lung datasets, respectively." (PMID 29212181, 2017).
stomach cancer (4 papers, 2021 to 2025). "IGF2BP3 directly recognizes and binds to the m6A modification site of METTL3-mediated HDGF mRNA and enhances the stability of HDGF, thereby promoting gastric tumor angiogenesis." (PMID 35572524, 2022).
thyroid tumor (4 papers, 2018 to 2023). A benign or malignant neoplasm affecting the thyroid gland. "These mutations are RET/PTC and THADA/IGF2BP3 translocations, which have been hypothesized as oncogenic events in thyroid neoplasms." (PMID 37444504, 2023). "This study investigated the impact of two gene fusions, RET/PTC and THADA/IGF2BP3, that have been described as oncogenic events in thyroid neoplasms." (PMID 37444504, 2023). "In thyroid tumors, the high expression of IGF2BP3 sustains IGF2 levels and leads to an increased sensitivity to OSI-906." (PMID 29731738, 2018).
type 2 diabetes (4 papers, 2018 to 2023). "Notably, several age-downregulated genes, such as Plxdc2, Igf1, Igf2bp3, and Igf1r, and upregulated genes, such as Adam19 and Tmem163, have been linked to IGF signaling or type 2 diabetes." (PMID 30180872, 2018). "Compared with IGF2BP1 and IGF2BP3, IGF2BP2 has been considered as a candidate gene for type 2 diabetes mellitus (T2D)." (PMID 36237306, 2022).
acute lymphoblastic leukemia (3 papers, 2020 to 2023). Leukemia with an acute onset, characterized by the presence of lymphoblasts in the bone marrow and the peripheral blood. "The RBP insulin-like growth factor 2 mRNA-binding protein 3 (IGF2BP3) has similarly been found to be overexpressed in mixed-lineage leukemia–rearranged (MLL rearranged) B-acute lymphoblastic leukemia (B-ALL) and to be associated with poorer outcomes and higher recurrence risks in these patients." (PMID 33228611, 2020). "IGF2BP3 is necessary for B-cell acute lymphoblastic leukemia (B-ALL) cell survival." (PMID 36076951, 2022).
brain tumors (3 papers, 2021 to 2023). "Accumulating evidence indicated that abnormal IGF2BP3 expression had a prognostic value in brain tumors." (PMID 34721530, 2021). "However, we have noted that a prognostic model containing eight genes, including IGF2BP3, for pediatric brain tumors has already been developed recently in a randomized controlled trial, which dramatically enhances the identification of those patients with a poorer prognosis by such gene signature." (PMID 36761737, 2023). "Many oncogenic RBPs such as hnRNPH1, IGF2BP3, HuR, PTB, and SNRPB have been identified and characterized in the context of brain tumors." (PMID 35011618, 2021).
breast invasive cancer (3 papers, 2021 to 2025). "A study comparing IGF2BP3 expression via IHC in 39 cases of invasive breast carcinoma with BRCA mutations and 54 cases of sporadic invasive breast carcinoma revealed that IGF2BP3 expression was more commonly observed in carcinomas with BRCA mutations." (PMID 40672753, 2025).
cholangiocarcinoma (3 papers, 2012 to 2026). A carcinoma that arises from the intrahepatic biliary tree (intrahepatic cholangiocarcinoma) or from the junction, or adjacent to the junction, of the right and left hepatic ducts (hilar cholangiocarcinoma). "Moreover, the IGF2BP3 promoter demethylated in CpG islands was a feature of intrahepatic cholangiocarcinoma compared with normal liver tissue." (PMID 37743642, 2023).
Cirrhosis (3 papers, 2014 to 2024). A chronic disorder of the liver in which liver tissue becomes scarred and is partially replaced by regenerative nodules and fibrotic tissue resulting in loss of liver function. "Elevated IGF2BP3 levels were associated with increased liver injury and fibrosis, as indicated by Col1A1 expression, suggesting that IGF2BP3 elevation may contribute to cirrhosis pathogenesis in humans." (PMID 39113232, 2024). "qPCR analysis of liver specimens from patients with cirrhosis and healthy donors revealed significantly higher IGF2BP3 levels in cirrhotic patients." (PMID 39113232, 2024).
mesothelioma (3 papers, 2020 to 2022). A usually malignant and aggressive neoplasm of the mesothelium which is often associated with exposure to asbestos. "Mesothelioma cells simultaneously transfected with IGF2BP3 siRNA and p27 siRNA showed a significant recovery in cell proliferation, when compared with cells transfected with IGF2BP3 siRNA alone." (PMID 35127504, 2021). "IGF2BP3 expression was significantly increased in mesothelioma cell samples compared with that in reactive mesothelial hyperplasia." (PMID 35127504, 2021). "First, we performed IGF2BP3 knockdown in mesothelioma cell lines (ACC-MESO1 and CRL-5915) using siRNA to analyze its biological functions, including cell proliferation, cell cycle, cell migration, and cell invasion." (PMID 35127504, 2021). "Next, when IGF2BP3 siRNA and p27 siRNA were simultaneously transfected into the cells, cell proliferation was significantly restored toward to that of mesothelioma cells transfected with only NC siRNA." (PMID 35127504, 2021). "When p27 siRNA and IGF2BP3 siRNA were simultaneously transfected into mesothelioma cells, there was an increase in the percentage of cells in the G1 phase of the cell cycle compared with the cell numbers after transfection with IGF2BP3 siRNA alone." (PMID 35127504, 2021). "In summary, IGF2BP3 is involved in the proliferation of mesothelioma cells by decreasing p27 expression, which regulates the progression from the G1 phase to S phase of the cell cycle." (PMID 35127504, 2021). "The mean transcript level of IGF2BP3 in mesothelioma increased by approximately 2-fold as shown in the scatter plot." (PMID 35127504, 2021). "All seven mesothelioma tissues and four mesothelioma cell lines showed high expression of IGF2BP3 compared with two reactive mesothelial hyperplasia tissues." (PMID 35127504, 2021). "This is the first study to investigate the biological functions of IGF2BP3 in mesothelioma cells." (PMID 35127504, 2021). "In mesothelioma cells without knockdown of IGF2BP3, the expression of p27 itself is usually a low level, suggesting that p27 knockdown alone did not cause significant changes in cell proliferation." (PMID 35127504, 2021).